SH3RF3 (SH3 domain containing ring finger 3)
Description:
Has E3 ubiquitin-protein ligase activity.
Synonyms: POSH2; SH3MD4; FLJ00204
Tractability: PROTAC: UniProt records ubiquitination sites on it; its protein half-life has been measured.
Gene: Protein-coding gene on chromosome 2 (109,129,205 to 109,504,634, forward strand). Ensembl gene ENSG00000172985.
Subcellular location (Human Protein Atlas): Nucleoplasm
Gene Ontology:
Molecular function: protein binding; ubiquitin protein ligase activity
Biological process: positive regulation of JNK cascade; protein autoubiquitination; negative regulation of apoptotic process; protein ubiquitination
Cellular component: nucleoplasm
Genetic constraint (gnomAD): Loss-of-function variants: 27 observed, 53.62 expected, observed/expected ratio (o/e) 0.5, 90% interval 0.37 to 0.69. The upper end of that interval is the gene's LOEUF score, 0.69, which puts it in group 2 of 6, group 1 being the genes least tolerant of losing a copy. Missense variants: 1,149 observed, 1,062.8 expected, observed/expected ratio (o/e) 1.08, 90% interval 1.03 to 1.13. Synonymous variants: 544 observed, 472.64 expected, observed/expected ratio (o/e) 1.15, 90% interval 1.07 to 1.24.
Homologues: Orthologues: chimpanzee SH3RF3 (99% identical), macaque SH3RF3 (98% identical), dog SH3RF3 (86% identical), mouse Sh3rf3 (83% identical), rat Sh3rf3 (83% identical), pig SH3RF3 (79% identical), rabbit SH3RF3 (72% identical), guinea pig SH3RF3 (71% identical), tropical clawed frog sh3rf3 (69% identical), zebrafish SH3RF3 (39% identical), Caenorhabditis elegans sorb-1 (14% identical), Caenorhabditis elegans B0303.7 (12% identical), and 3 more. Paralogues in human: SH3RF1 (48% identical), SH3RF2 (27% identical), SORBS1 (16% identical), SORBS2 (14% identical), SORBS3 (12% identical), SH3D19 (11% identical), SH3GLB2 (8% identical), SH3GL1 (7% identical), NCF4 (7% identical), SH3GL2 (7% identical), SH3GL3 (7% identical), SH3GLB1 (7% identical).
Diseases named in the same sentence as SH3RF3 in open-access papers:
SH3RF3 is named in the same sentence as 19 diseases in open-access papers, as found by Europe PMC text mining. Sharing a sentence is not in itself a finding about the gene and the disease. The quoted sentences say what the papers report.
breast carcinoma (4 papers, 2020 to 2025). "Analysis of clinical samples indicated that SH3RF3 level was correlated with several kinds of disease including breast cancer." (PMID 34486645, 2021). "In Py8119, a murine breast cancer cell line derived from the PyMT-driven tumors, Sh3rf3 upregulation was also observed in the ALDH+ subpopulation versus the ALDH− counterpart, and Sh3rf3 overexpression increased the capacity of tumorsphere formation by Py8119." (PMID 32427938, 2020). "In this study, we show that the scaffold protein SH3RF3 is highly expressed in breast cancer CSCs and reveal its function to enhance the cancer cell stemness by regulating PTX3." (PMID 32427938, 2020). "By transcriptomic screening of clinical tumors and cancer cell lines, we found that the expression of SH3RF3 was consistently correlated with CSC properties of breast cancer cells." (PMID 32427938, 2020). "Patient-derived tumor cells of three breast cancers were infected with control or SH3RF3-expressing retroviruses and seeded in matrigel with organoid culture media." (PMID 32427938, 2020). "Here, the authors show that the scaffold protein SH3RF3 enhances the stem-like properties of breast cancer by facilitating activation of the JNK-JUN pathway and PTX3 expression." (PMID 32427938, 2020). "Here we showed that in breast cancer cells SH3RF3 also plays a role in the complex and contributes to JNK phosphorylation." (PMID 32427938, 2020). "In summary, our data confirmed that SH3RF3 plays a positive role in BCSC maintenance and is clinically associated with CSC enrichment and poor prognosis of breast cancer." (PMID 32427938, 2020). "Here we report a previously unidentified role of SH3RF3 in stemness regulation of breast cancer." (PMID 32427938, 2020). "In this study, we found SH3RF3 could upregulate the expression of Pentraxin 3 (PTX3) to promote stem-like traits of breast cancer cells." (PMID 32427938, 2020). "In conclusion, our work elucidates the role and molecular mechanism of SH3RF3 in CSCs of breast cancer, and might provide opportunities for CSC-targeting therapy." (PMID 32427938, 2020). "PTX3 is regulated by SH3RF3 through JNK-JUN pathway, thus enhancing breast cancer stem cell properties." (PMID 41479916, 2025). "Altogether, these results suggested the role of SH3RF3 in CSC promotion and maintenance in breast cancer cells." (PMID 32427938, 2020). "By transcriptomic analysis, we identify a scaffold protein SH3RF3 (also named POSH2) that is upregulated in CSCs of breast cancer clinical tumors and cancer cell lines, and enhances the CSC properties of breast cancer cells." (PMID 32427938, 2020). "The ssGSEA analysis showed that the genes with differential expression by SH3RF3 and PTX3 overexpression were coordinately expressed in breast cancer cell lines." (PMID 32427938, 2020). "Moreover, the high expression of SH3RF3 in tumor tissues was correlated with the increases CSC number and weak prognosis of breast cancer." (PMID 34486645, 2021). "Thus we studied whether the interaction between SH3RF3 and JNK in breast cancer cells is dependent on JIPs." (PMID 32427938, 2020). "We found that SH3RF3 could interact with all three JIP family members JIP1, JIP2, and JIP3 in 293T; however, JIP3 was the only JIP gene expressed in breast cancer cells MCF10AT." (PMID 32427938, 2020).
Alzheimer disease (2 papers, 2023 to 2024). A progressive, neurodegenerative disease characterized by loss of function and death of nerve cells in several areas of the brain leading to loss of cognitive function such as memory and language. "Interestingly, two variants associated with low z-insulin in the present study were located on RBFOX1 and SH3RF3, genes that have previously been shown to be related to brain amyloidosis in preclinical Alzheimer’s disease and to late-onset Alzheimer’s disease, respectively." (PMID 37420130, 2023).
gastric cancer (2 papers, 2020 to 2022). A primary or metastatic malignant neoplasm involving the stomach. "Similar results were observed in the organoid culture of four human gastric cancers, corroborating a role of SH3RF3 to promote CSC features of clinical tumor cells." (PMID 32427938, 2020).
schizophrenia (2 papers, 2019 to 2023). A major psychotic disorder characterized by abnormalities in the perception or expression of reality. "Similarly, SH3RF3 has been associated with general cognitive ability, schizophrenia, and eosinophilia." (PMID 37258616, 2023).
acute lymphoblastic leukemia (1 paper, 2022). Leukemia with an acute onset, characterized by the presence of lymphoblasts in the bone marrow and the peripheral blood. "The aberrant expression of SH3RF3 was significantly associated with a higher probability of long-term survival in acute lymphoblastic leukemia." (PMID 35813831, 2022).
anxiety disorder (1 paper, 2025). A category of psychiatric disorders which are characterized by anxious feelings or fear often accompanied by physical symptoms associated with anxiety. "Interestingly, the RPSAP52, SLC47A2, SH3RF3 genes have also been implied in a previous cross-anxiety disorder EWAS." (PMID 40281224, 2025).
breast invasive ductal carcinomas (1 paper, 2020). "Next, we assessed the expression of SH3RF3 and CD44 at the protein level in a Qilu cohort of 40 breast invasive ductal carcinomas by immunofluorescence (IF) staining." (PMID 32427938, 2020).
Insulin resistance (1 paper, 2023). Increased resistance towards insulin, that is, diminished effectiveness of insulin in reducing blood glucose levels. "Two variants associated with the 15th percentile of z-insulin were located on genes previously linked with insulin secretion and beta cell function (RBFOX1) and measures of insulin resistance (SH3RF3)." (PMID 37420130, 2023).
leukemia (1 paper, 2020). A malignant (clonal) hematologic disorder, involving hematopoietic stem cells and characterized by the presence of primitive or atypical myeloid or lymphoid cells in the bone marrow and the blood. "Blv-miR-B1-5p, may have a role in inhibiting expression of SH3RF3 to establish leukemia in cattle." (PMID 33195511, 2020).
lung carcinoma (1 paper, 2020). "However, the roles of these POSH members in cancer are unexplored, although dysregulation of SH3RF1 and SH3RF3 has been implicated in lung cancer and leukemia." (PMID 32427938, 2020).
cancer (6 papers, 2020 to 2024). A tumor composed of atypical neoplastic, often pleomorphic cells that invade other tissues. "Further, we analyzed the in vivo tumorigenic capacity of SH3RF3-overexpressing cancer cells via limiting dilution assays." (PMID 32427938, 2020). "More importantly SH3RF3 not only promotes, but also is required to maintain the stem-like features of cancer cells." (PMID 32427938, 2020). "The follow-up research showed that TRPV4 might affect the generation of cancer by influencing gene expression or function of SH3RF3, CHFR, ZTB1, and TRAFD1." (PMID 35813831, 2022). "However, the functional role and mechanism of SH3RF3 in pathological processes, especially in cancer, are largely unexplored." (PMID 32427938, 2020). "In addition, a list of known JUN-target genes, including MMP3, CD44, EGFR, ENPP246, and MGST147, were markedly upregulated in cancer cells with SH3RF3 overexpression." (PMID 32427938, 2020). "Moreover, matrine exerted its anti-cancer effects in PTC via regulating miR-192-5p/SH3RF3 pathway." (PMID 34486645, 2021). "Therefore, we further investigated whether the anti-cancer effects of matrine was correlated with the miR-192-5p/SH3RF3 pathway." (PMID 34486645, 2021). "In the meantime, matrine, an alkaloid extracted from herb, exerted its anti-cancer effects in PTC cells dependent on increase in miR-192-5p expression and decrease in SH3RF3 expression." (PMID 34486645, 2021). "We also demonstrate that SH3RF3 contributes to the assembly of MKK-JIP-JNK complex, leading to activation of JNK and upregulation of PTX3 expression for CSC regulation in cancer cells." (PMID 32427938, 2020). "Although the detailed mechanism of SH3RF3 to mediate the interaction of JNK and MKK is yet to be delineated, our study will expand our understanding of the POSH family proteins and CSC regulation in cancer." (PMID 32427938, 2020). "This discovery will enrich our understanding on JNK signaling, and it warrants further investigation whether SH3RF3 is a genuine component of JNK signaling complex or its role in JNK and CSC regulation is context-specific in cancer cells." (PMID 32427938, 2020). "Notably, SH3RF3, which had not been previously implicated in CSC regulation, was among the genes highly upregulated in CSC-enriched tumors and cancer cell sublines." (PMID 32427938, 2020).
tumor (2 papers, 2020 to 2021). "In summary, it is the first study to declare that miR-192-5p played a tumor suppressive role in PTC cells via modulating SH3RF3 expression." (PMID 34486645, 2021). "A similar phenomenon was also observed for HMLER cells in which SH3RF3 overexpression led to enhance in vivo tumor incidence in the limiting dilution assay." (PMID 32427938, 2020).
SH3RF3 also shares sentences with these, for which no sentence is quoted: papillary thyroid carcinoma (2 papers); eosinophilia (1); HIV-1 infection (1); melanoma (1); monoclonal gammopathy of undetermined significance (1); multiple myeloma (1); Parkinson (1).